IDO1 (indoleamine 2,3-dioxygenase 1)
Diseases named in the same sentence as IDO1 in open-access papers (continued):
Sharing a sentence is not in itself a finding about the gene and the disease.
tumor (continued). "IDO1 immuno-expression has been observed not only in tumor cells but in the surrounding stroma, as well." (PMID 36879122, 2023). "DE miRNAs corresponded to higher level of IDO1 favors tumor survival, progression, and immune escape." (PMID 37284323, 2023). "Secondly, we investigated the significance of IDO1+ macrophages in peripheral blood mononuclear cells (PBMCs) and compared their abundance between tumour tissue and healthy adjacent tissue prospectively." (PMID 35963900, 2023). "Epacadostat is a potent and selective IDO1 inhibitor, which has displayed the ability to restore anti-tumor T cell immunity and synergizes with immune checkpoint inhibitors in preclinical models and in early phase trials." (PMID 37122718, 2023). "The induction of the IDO1-Kyn-AhR axis by p27 prevents IFN-γ-induced STAT1 signaling-mediated tumor cell apoptosis and activates the dormancy program in TRCs." (PMID 37380989, 2023). "Thereby IDO1 immunolabelling in tumors has been seen to show three distinct cellular expression patterns which includes expression in tumor cells, interstitial cells in lymphocyte-rich areas in the tumor stroma or endothelial cells." (PMID 36879122, 2023). "The combined ERO1a and IDO1 inhibition also resulted in the upregulation of several other anti-tumor immune effects." (PMID 38187398, 2023). "We are able to show the presence of lymphocytes and immune checkpoint markers especially PD-L1, ICOS and IDO1 within tumour samples and their significance in terms of patient survival." (PMID 37527282, 2023). "Presently, IDO1 is overexpressed in a variety of tumor tissues, and IDO1 has emerged as a potential target for studying tumor immunosuppression." (PMID 37408559, 2023). "The antitumor capacity of IDO-1 inhibitors primarily stems from their regulation of immune cells, resulting in increased infiltration of tumor-infiltrating lymphocytes." (PMID 37626777, 2023). "Tumoral IDO1 is collectively thought to be a modulator that bridges inflammation, vascularization, and immune escape to promote primary and metastatic tumor outgrowth." (PMID 37817770, 2023). "Cyclooxygenase-2 (COX-2) and prostaglandin E2 (PGE2) expressions drive constitutive expression of IDO1 in many human tumor cells via the PKC and PI3K pathways." (PMID 36983678, 2023). "Compared with the NS group and IR780 + Laser (L) (IR780 + L) group, the N-I-Lip+Laser (N-I-Lip+L) group upregulated the expression of IDO1 in both tumour tissues and LNs." (PMID 37076492, 2023). "The available data also show that human tumor cells are more sensitive to gemcitabine with simultaneous IDO1 downregulation." (PMID 38201550, 2023). "IDO1 depleted tryptophan and increased kynurenine in the tumor microenvironment, which decreased tumor-infiltrating T cell activity due to GCN2 kinase activity." (PMID 36798123, 2023). "Immunosuppressive enzyme indoleamine 2,3-dioxygenase 1 (IDO1) participates in tumor immune tolerance and promotes tumor progression, while the study of IDO1 in OS is limited." (PMID 37284323, 2023). "Previous studies have shown that the upregulation of IDO1 expression is positively correlated with poor prognosis and tumor progression." (PMID 36599884, 2023). "In cancer, a disease with multiple parallels to PKD, plasma kynurenine levels and tumor expression of IDO1 negatively correlate with cancer survival and clinical outcome." (PMID 36422996, 2023). "IDO1-inhibiton even protected tumour cells from switching off protein translation and Melanocyte Inducing Transcription Factor (MITF) production by IFN-γ." (PMID 37503572, 2023). "These limitations can be addressed by quantifying the expression of IDO1 enzyme in tumour tissue using immunohistochemistry and/or the flow cytometry." (PMID 37041200, 2023). "ERO1a and IDO1 independently shape the myeloid cell compartment, but their roles in modulating the tumor secretome within myeloid cell interactions are underexplored." (PMID 38187398, 2023).
tumor (continued). "As concerns macrophages, we observed an increased number of CD68+CD163+ and CD68+IDO1+ cells in MUC1H tumor samples, revealing that TAMs were M2-polarized and able to produce KYN." (PMID 36902242, 2023). "And it can be seen that targeting IDO1, which is considered one of the meaningful strategies for treating tumors, can inhibit tumor development by restoring tumor immunity." (PMID 38264667, 2023). "Increased IDO1 levels, reflected by decreased Trp and elevated Kyn concentrations in the peripheral blood has been observed to be related to tumor progression and poor clinical outcome." (PMID 36879122, 2023). "Their respective roles in myeloid cell infiltration were demonstrated with ERO1a modulating the hypoxic tumor compartment and IDO1 modulating the myeloid cell compartment." (PMID 38187398, 2023). "IDO1 expression is present not only in tumor cells but also in endothelial cells, fibroblasts, and immune cells that infiltrate the TME." (PMID 37334368, 2023). "In particular, we highlight how IDO1 acts as an integrative node for multiple ‘cancer hallmarks’, shaping a tumor-promoting inflammatory environment through altered cellular metabolism that promotes both immune escape and neovascularization." (PMID 37182174, 2023). "It was identified that epacadostat potently activates AhR-mediated signaling, inducing the nuclear translocation of AhR and the upregulation of IDO1 expression in both tumor cells and splenic T cells, leading to immunosuppression." (PMID 37122718, 2023). "It is also possible that IDO1 is controlled by cell-intrinsic pathways that “hijack” IDO1 for enhanced tumor cell metabolism and survival." (PMID 37196768, 2023). "IDO1 is expressed in various cell types, leading to KP activation in different tissues and cells, like dendritic cells, macrophages, and tumor cells." (PMID 38201667, 2023). "In tumor cells, kynurenine accentuates the cell cycle, and IDO1 inhibition significantly reduces the number of cells in S phase." (PMID 36653774, 2023). "Indoleamine 2,3-dioxygenase 1 (IDO1), expressed by both tumor and immune cells, is the most extensively studied amino acid-metabolizing enzyme relevant to cancer immunology." (PMID 36765849, 2023). "In conclusion, our study provides evidence supporting the simultaneous targeting of ERO1a and IDO1 as a promising strategy for modulating the myeloid cell compartment and altering the tumor secretome in PDAC." (PMID 38187398, 2023). "IDO-1 inhibitor research is already well developed in the field of oncology, with IDO-1 playing a potential role in tumor immune escape." (PMID 36831835, 2023). "In this study, a self-augmented reactive oxygen species (ROS) responsive nanocarrier with immunogenic inducer paclitaxel (PTX) and indoleamine 2,3-dixoygenase 1 (IDO1) blocker 1-methyl-d, L-tryptophan (1-MT) co-entrapment was developed for tumor rejection." (PMID 36927803, 2023). "Still, the role that IDO1 plays in shaping tumor-promoting inflammation appears to be uniquely consequential, raising the question Why IDO1?" (PMID 37182174, 2023). "Another effective approach involves the use of hybrid micelles (SK/siIDO1-HMs) for the delivery of shikonin and siRNA targeting IDO-1 knockdown, which have shown promising results in suppressing Tregs in the tumor microenvironment." (PMID 38004600, 2023). "To verify IDO1 expression level was correlated with EC, we prepared tissue microarrays based on tumor tissues (n = 61) and normal tissues of clinical patients and performed immunohistochemistry to explore the expression of this gene." (PMID 37903782, 2023). "Expression of IDO1 by tumor, Bregs, and TAM cells promotes the conversion of tryptophan to kynurenine, thus resulting in tryptophan deficiency in TME." (PMID 37568713, 2023). "Inhibition of ERO1a and IDO1 also resulted in identification of 203 and 65 more secreted proteins at D5 respectively, signifying their inhibition upregulated the tumor spheroid secretome." (PMID 38187398, 2023).
tumor (continued). "AhR activation by the IDO1/TDO2 product kynurenine promotes a tumor microenvironment that is defective in recognition and eradication of the cancer cells." (PMID 37830596, 2023). "IDO1 is the most widely studied Trp‐catabolizing enzyme and can be detected in tumor, immune, and endothelial cells in various tissues, including the intestine, pancreas, kidney, and central nervous system." (PMID 37148546, 2023). "This review focuses on the IDO1 enzyme as one important determinant of a tumor-promoting inflammatory environment." (PMID 37182174, 2023). "Elevated IDO1/TDO activity has been reported in tumour cells and blood sampled from patients with cancer, including glioblastoma, colorectal cancer, breast cancer and liver cancer." (PMID 37041200, 2023). "This further verified that NAMPT and ACAT1 play biological roles mainly by regulating the energy metabolism of various cell types, whereas IDO1 affects tumor progression by regulating the activity of immune cells." (PMID 37954600, 2023). "Indoleamine 2,3-dioxygenase 1 (IDO1) is an immunosuppressive enzyme involved in tumor immune escape." (PMID 38201582, 2023). "To study under defined conditions the effect of IDO1 inhibition on tumor cells that are under T cell attack, we made use of a co-culture system that we previously established." (PMID 36812891, 2023). "After that, IDO1 expression was significantly reduced in PBMCs (t test, p = 0.01), potentially due to the removal of the immunosuppressive tumour." (PMID 35963900, 2023). "In tumor microenvironments, IL4i1 and IDO1 have overlapping expression patterns, especially in myeloid cells, suggesting the two enzymes control a network of tryptophan-specific metabolic events." (PMID 37196768, 2023). "Among them, IDO-1 is widely expressed in tumor cells and inflammatory/antigen presenting cells (APCs), induces the production of Kyn by catabolizing tryptophan, the ratio of serum Kyn to tryptophan reflects IDO-1 activity to some extent." (PMID 38318507, 2023). "When ctDNA detection was combined with the level of tumour mutational burden (TMB) and a tumour-derived interferon signature (including HLA-DRA, CXCL9/10/11, GZMA, PRF1, CCR5, IFNG, IDO1 and STAT1), the predictive value of the combined score was enhanced." (PMID 38201222, 2023). "Studies of immunometabolism and inflamometabolism have revealed a role for the tryptophan catabolizing enzyme IDO1 as a core element in tumor-promoting inflammation." (PMID 37182174, 2023). "Elevated kynurenine levels and IDO1 upregulation promote an immunosuppressive microenvironment and thus allow tumor escape from immune destruction." (PMID 36422996, 2023). "Understanding IDO1 in this light raises the question of why such a powerful tumor-promoting metabolic enzyme, disconnected from the basic housekeeping function of maintaining tryptophan homeostasis, exists in the first place." (PMID 37182174, 2023). "Pre-clinical evidence suggested IDO1 as a key mechanism of acquired immune tolerance, by affecting several immune cells within the tumor microenvironment." (PMID 36812891, 2023). "Another IDO1 inhibitor increased IDO1 activity in tumor cells leading to increased KYN products, which suppress CD4+ Th1 cells, Th17 cells, CTLs, and NK cells, all of which are overexpressed in malignant tissue." (PMID 37795038, 2023). "IDO1 activity has been studied in NSCLC where it has been seen to be directly proportional to tumor stage and aggressiveness." (PMID 36879122, 2023). "IDO1 enzyme can regulate immunosuppression in the tumor microenvironment (TME) by recruiting myeloid-derived suppressor cells (MDSCs) via the regulatory T cells (Tregs)." (PMID 37226257, 2023). "In the six trials with BrCa patients, only half of the six trials assessed IDO1 status of the tumour during the trial." (PMID 37041200, 2023).
tumor (continued). "Possible therapeutic strategies include checkpoint blockade, e.g., blockade of CTLA-4, PD1, PD-L1; targeting angiogenesis, e.g., anti-VEGF drugs; or inhibiting tumor-specific metabolic pathways, e.g., IDO1 inhibitors." (PMID 37427115, 2023). "IDO1 expression was shown earlier to be increased not only in RCC tumor cells, but also in the microenvironment of human RCC compared to normal kidney tissues." (PMID 37370768, 2023). "Tumor‐infiltrating CTL‐secreted IFN‐γ can induce adaptive immune resistance by activating IDO‐1 and PD‐L1." (PMID 36599655, 2023). "For example, Epacadostat can inhibit the secretion of KYN by tumor cells that mainly express IDO1, but it hardly affects the tumor cells that mainly express TDO." (PMID 38264667, 2023). "Here, we showed that B16F10 tumor express IDO1 so using Lip-EPA will enhance the efficacy of vaccine therapy." (PMID 37037839, 2023). "In fact, IDO1 has a role in establishing an immunosuppressive tumor microenvironment in many tumors through its enzymatic activity, which causes tryptophan depletion and the production of kynurenine and several metabolites (kynurenines)." (PMID 37122718, 2023). "IDO‐1 catalyses the oxidation of tryptophan (Trp) to produce kynurenine (Kyn), and Trp starvation and Kyn accumulation in the tumour microenvironment lead to T‐cell depletion and dysfunction." (PMID 37712124, 2023). "IDO1 plays an important role in immune tolerance by depleting tryptophan in the tumor microenvironment and inhibiting the proliferation of effector T cells, which makes it an important emerging biomarker for cancer immunotherapy." (PMID 37509627, 2023). "In the present study, we observed a modest reduction in tumor burden when using the IDO-1 inhibitor DL-1MT as a monotherapy (panel K14E7E2 + IDO1i)." (PMID 37626777, 2023). "Because blocking CTLA-4 (using abatacept or the antibody ipilimumab) is now a well-recognized anti-cancer treatment, it is clear that IDO1 activation is intimately involved in both autoimmune function and tumor development." (PMID 37296860, 2023). "The RNAseq from tumor tissue (n = 162) and normal tissue (n = 11) samples based on The Cancer Genome Atlas (TCGA) database was analyzed and founding that IDO1 was generally highly expressed in EC (P < 0.001)." (PMID 37903782, 2023). "The link between IDO1 and macrophages was investigated by flow cytometry in tumour tissue, healthy adjacent tissue and peripheral blood mononuclear cells (PBMCs)." (PMID 35963900, 2023). "IDO (1 and/or 2) expression in EC correlates with the number of nodal metastases, low number of CD8pos T cells and natural killer (NK) cells within the tumor, and decreased PFS." (PMID 37046702, 2023). "mIHC results showed that Abrine co-treated with anti-PD-1 antibody increased CD8+ cytotoxic T cells infiltration in tumor cells, decreased Foxp3+ Treg cells, and inhibited IDO1 and PD-L1 expression." (PMID 37334368, 2023). "Our results showed that the combination of Lip-EPA and Lip-gp100 was significant on IDO1 inhibition, the immunostimulatory effects, as well as preclinical outcomes, including survival and tumor growth rate." (PMID 37037839, 2023). "IDO1, one of tryptophan metabolizing enzymes, was demonstrated to correlate with low tumor infiltration of T cells in colorectal cancer, ovarian cancer, and endometrial cancer." (PMID 36816023, 2023). "According to reports, small compounds such as EZH2 inhibitors that disrupt epigenetic regulation or IDO1 inhibitors that modulate metabolic pathways have boosted the anti-tumor immunity induced by PD-1/PD-L1 inhibitors." (PMID 38106415, 2023). "Recent studies also indicate that IDO1 plays a significant role in enhancing tumour growth and inhibiting tumour cell apoptosis via the PI3K/AKT signalling pathway." (PMID 36980527, 2023). "IFN-r is expressed by activated T cells and can induce IDO1 expression in most tissues and cell types, resulting in an inhibition of T cell responses to tumor cells." (PMID 36983678, 2023).
tumor (continued). "IFN-γ promotes the expression of IDO1 in primary and metastatic tumor cells, intratumoral endothelial cells, immune cells in the peritumoral stroma, and tumor-draining lymph nodes." (PMID 37444608, 2023). "IDO1 metabolism can deplete the tryptophan from the tumor microenvironment, leading to the impairment of T-cells activation, thereby achieving immunosuppression of the tumor microenvironment and escaping attack by the host immune system." (PMID 36925967, 2023). "Epacadostat has been shown to have the greatest efficacy in inhibiting IDO1 activity and in shifting the immune population towards tumour targeting CD8 + T cells." (PMID 37041200, 2023). "Currently, inhibitors targeting IDO1 are being explored in clinical trials with the aim to undermine the immunosuppressive environment it creates, thereby enhancing anti-tumor immune responses and potentially improving the prognosis in various cancers." (PMID 37980528, 2023). "Measurement of tumor volume and body weight revealed that IDO1 overexpression drove tumor growth, whereas CXCL10 knockdown showed an inhibitory effect (P < 0.01)." (PMID 37903782, 2023). "Indoleamine 2, 3-dioxygenase 1 (IDO1), is a rate-limiting enzyme of tryptophan catabolism, that is mainly activated in tumor cells, stromal cells, and antigen-presenting cells." (PMID 38169949, 2023). "IDO1 is highly expressed in tumor cells and contributes to the establishment of a local immunosuppressive TME by enabling immune tolerance." (PMID 36874131, 2023). "Consistently, tumor tissues in IDO1 overexpression and CXCL10 knockdown groups showed high and low expression of KI67, respectively." (PMID 37903782, 2023). "Recently, the analysis of the OS database found that the immune checkpoint IDO1 and PD-1, PD-L1 and B7-H3 were expressed in the tumor samples, among which the expression of IDO1 and B7-H3 was significantly related to the poor prognosis of patients." (PMID 37284323, 2023). "The presence of different IL4i1+ and IDO1+ myeloid cells in tumor-draining lymph nodes is less understood but given that many DCs are migratory, this is an important point to consider." (PMID 37196768, 2023). "IFN-γ can promote immunosuppressive effects through increasing PD-L1 and indoleamine 2, 3-dioxygenase 1 (IDO1) expression in tumours." (PMID 37503572, 2023). "Activation of AhR on the tumour by KYN induces an inflammatory positive autocrine feedback loop (IDO1-AhR-IL-6-STAT3 signalling pathway) to enhance tumour growth." (PMID 37041200, 2023). "Together with the previous reports that IDO1 is immunosuppressive against anti-tumor immunity, we believed that there was a necessity to block IDO1 during HSV-1-based virotherapy." (PMID 37296221, 2023). "IDO1 is an intracellular immunomodulatory enzyme that promotes immunosuppression, tolerance, and tumor escape by catabolizing tryptophan." (PMID 38139250, 2023). "The mRNA and protein expressions of IDO1 in OS tumor tissues were significantly higher than those in normal bone tissues excised from control multi fingered patients." (PMID 37284323, 2023). "In different tumor settings, IDO1 expression has been detected in a variety of cell types, including tumor cells as well as in various stromal cells, (DCs, macrophages, and monocytes)." (PMID 37182174, 2023). "IDO1 is a type of tryptophan catabolic enzyme, known for inactivating T cells and promoting tumor immunotolerance." (PMID 37671947, 2023). "Research has demonstrated a correlation between the upregulation of IDO1 in both human tumors and antigen-presenting cells of the host and unfavorable prognosis, as well as parameters indicative of tumor progression." (PMID 37630387, 2023). "Dual inhibition of IDO1/TDO2 in CR mice suppressed tumor growth to a greater degree than IDO1 inhibition alone." (PMID 37226257, 2023). "Expression of IDO1 was more variable, with expression on sub-populations of lymphocytes in the stroma but also occasional strong expression on intra-tumoural nests of epithelial cells." (PMID 37527282, 2023).